RASIP1 (Ras interacting protein 1)
Description:
Required for the proper formation of vascular structures that develop via both vasculogenesis and angiogenesis. Acts as a critical and vascular-specific regulator of GTPase signaling, cell architecture, and adhesion, which is essential for endothelial cell morphogenesis and blood vessel tubulogenesis. Regulates the activity of Rho GTPases in part by recruiting ARHGAP29 and suppressing RhoA signaling and dampening ROCK and MYH9 activities in endothelial cells (By similarity). May act as effector for Golgi-bound HRAS and other Ras-like proteins. May promote HRAS-mediated transformation. Negative regulator of amino acid starvation-induced autophagy.
Synonyms: Rain; FLJ20401
Tractability: Small molecule: a structure with a bound ligand is known. PROTAC: ubiquitination databases record sites on it.
Gene: Protein-coding gene on chromosome 19 (48,720,571 to 48,740,611, reverse strand). Ensembl gene ENSG00000105538.
Subcellular location: Cytoplasm, perinuclear region; Golgi apparatus, Golgi stack
Gene Ontology:
Molecular function: GTPase binding; protein binding; protein homodimerization activity; protein serine/threonine kinase inhibitor activity
Biological process: negative regulation of autophagy; negative regulation of membrane permeability; negative regulation of Rho protein signal transduction; positive regulation of integrin activation; angiogenesis; branching morphogenesis of an epithelial tube; vasculogenesis; signal transduction
Cellular component: cell-cell junction; protein-containing complex; Golgi stack; perinuclear region of cytoplasm
Genetic constraint (gnomAD): Loss-of-function variants: 19 observed, 61.94 expected, observed/expected ratio (o/e) 0.31, 90% interval 0.21 to 0.45. The synonymous counts are far from expectation, so gnomAD's model fits this gene poorly and the ratio says little. Missense variants: 1,157 observed, 1,108.1 expected, observed/expected ratio (o/e) 1.04, 90% interval 0.99 to 1.1. Synonymous variants: 608 observed, 508.7 expected, observed/expected ratio (o/e) 1.2, 90% interval 1.12 to 1.28.
Homologues: Orthologues: chimpanzee RASIP1 (99% identical), macaque RASIP1 (98% identical), dog RASIP1 (98% identical), pig RASIP1 (96% identical), rat Rasip1 (94% identical), mouse Rasip1 (94% identical), guinea pig RASIP1 (92% identical), rabbit RASIP1 (57% identical), zebrafish rasip1 (43% identical), tropical clawed frog rasip1 (22% identical). Paralogues in human: RADIL (30% identical).
Diseases named in the same sentence as RASIP1 in open-access papers:
RASIP1 is named in the same sentence as 14 diseases in open-access papers, as found by Europe PMC text mining. Sharing a sentence is not in itself a finding about the gene and the disease. The quoted sentences say what the papers report.
cerebral cavernous malformation (2 papers, 2015 to 2016). A disorder characterized by malformations in the structure of the capillaries in the brain. "In vitro studies have implicated KRIT1/CCM1, a protein mutated in cerebral cavernous malformations (CCM), RASIP1 and an actin-cytoskeleton linker Canoe/Afadin as Rap1 effectors controlling cell-cell junction formation and maintenance." (PMID 26714318, 2015). "Src activity has been reported to inhibit the Rho/Rock pathway, a pathway also inhibited by Pak2/Pak4, Rasip1/Arhgap29, and the cerebral cavernous malformation (CCM) proteins, CCM1 and CCM2." (PMID 26812085, 2016).
lung carcinoma (2 papers, 2018 to 2023). "A GTPase binding protein, Ras interacting protein 1 (RASIP1), has been reported with a tumor-promoting role in lung cancer cells, and its role in lymphoma remains unknown." (PMID 36967521, 2023).
COVID-19 (1 paper, 2023). A disease caused by infection with severe acute respiratory syndrome coronavirus 2. "As a result, increased abundance of Ruminococcus torques coupled with the decreased RASIP1 expression were associated with the disruption of cell barrier and increased permeability, thereby ultimately increase the risk of COVID-19 worsening which was consistent with our MR results." (PMID 37662924, 2023). "Further analysis revealed that only RASIP1 expression had a higher colocalization probability with severe COVID-19." (PMID 37662924, 2023). "In addition, Ruminococcus torques abundance was colocalized with severe COVID-19 (PP.H4 = 0.77) and the colon expression of permeability related protein RASIP1 (PP.H4 = 0.95)." (PMID 37662924, 2023).
diffuse large B-cell lymphoma (1 paper, 2023). "The analysis of medical databank shows that RASIP1 is upregulated in diffuse large B-cell lymphoma (DLBCL) specimens." (PMID 36967521, 2023).
lymphoma (1 paper, 2023). A malignant (clonal) proliferation of B- lymphocytes or T- lymphocytes which involves the lymph nodes, bone marrow and/or extranodal sites. "The present study suggests RASIP1 as a potential therapeutic target of lymphoma." (PMID 36967521, 2023). "The transcription of RASIP1 was inhibited by FOXO3, a lymphoma-suppressing transcription factor." (PMID 36967521, 2023).
ovarian insufficiency (1 paper, 2020). "Interestingly, a set of 5 proteins (KHDC3L, SRSF8, PNO1, RASIP1, and MORC2) exhibited a significant association with ovarian insufficiency in this cohort." (PMID 32410729, 2020).
cancer (2 papers, 2023 to 2024). A tumor composed of atypical neoplastic, often pleomorphic cells that invade other tissues. "Recent studies have found that RASIP1 controls the motility of not only endothelial cells but also some tumor cells, such as lung cancer, suggesting that RASIP1 may be involved in the malignancies of cancer cells." (PMID 36967521, 2023). "Moreover, we also found that the expression of RASIP1 is regulated by forkhead box O3 (FOXO3), which has been reported with a cancer suppressive role in multiple tumors, including DLBCL20." (PMID 36967521, 2023).
infection (2 papers, 2021 to 2022). The state of being infected such as from the introduction of a foreign agent such as serum, vaccine, antigenic substance or organism. "Interestingly, significantly elevated expression of six above-mentioned associated genes (Pmepa1, Mamstr, Rasip1, Tpm1, Itih4 and Ogdhl) in mice total liver tissues was also observed from the seventh week (S. japonicum spawn in large numbers) after infection." (PMID 35493725, 2022).
tumor (2 papers, 2023 to 2024). "In addition, our results demonstrated that the transcription of RASIP1 was negatively regulated by FOXO3, which has been reported as an anti-tumor factor in multiple cancer cells." (PMID 36967521, 2023).
RASIP1 also shares sentences with these, for which no sentence is quoted: Burkitt lymphoma (1 paper); cardiovascular disease (1); learning disabilities (1); melanoma (1); psoriasis (1).